SNORD116-22 (small nucleolar RNA, C/D box 116-22)
Synonyms: HBII-85-22
Gene: Small nucleolar RNA gene on chromosome 15 (25,089,923 to 25,090,014, forward strand). Ensembl gene ENSG00000275127.
Gene Ontology:
Biological process: RNA processing
Cellular component: nucleolus
Homologues: Orthologues: macaque SNORD116 (98% identical), guinea pig SNORD116 (89% identical), guinea pig SNORD116 (85% identical). Paralogues in human: SNORD116-17 (99% identical), SNORD116-19 (99% identical), SNORD116-14 (98% identical), SNORD116-15 (98% identical), SNORD116-18 (98% identical), SNORD116-20 (98% identical), SNORD116-21 (98% identical), SNORD116-16 (96% identical), SNORD116-12 (92% identical), SNORD116-23 (92% identical), SNORD116-24 (92% identical), SNORD116-11 (89% identical), and 20 more.